CIP2A (cellular inhibitor of PP2A)
Diseases named in the same sentence as CIP2A in open-access papers (continued):
Sharing a sentence is not in itself a finding about the gene and the disease.
tumor (continued). "Furthermore, CIP2A expression can be demonstrated in tumor samples from TNBC patients." (PMID 22537901, 2012). "CIP2A correlates positively with p-AKT, CD31, and E-cadherin, and negatively with pAMPK, suggesting its role in tumor proliferation, angiogenesis, epithelial plasticity, and metabolic suppression." (PMID 40943297, 2025). "Together, these findings provide a mechanistic rationale for targeting the CIP2A-TOPBP1 axis, as well as downstream repair pathways involving SLX4 and Polθ, particularly in tumours that exhibit elevated replicative stress." (PMID 41309571, 2025). "Cucurbitacin B degrades EGFR and downregulates the CIP2A/PP2A/AKT axis, inhibiting growth and invasion of gefitinib-resistant NSCLC and reducing xenograft tumor volume." (PMID 40943297, 2025). "Through inhibition of PP2A, CIP2A drives dysregulation of signalling pathways, since it can interact with other oncoproteins such as MYC, Akt, as well as mTOR to encourage tumour progression." (PMID 40594400, 2025). "There is evidence that the knockdown of these inhibitors restored the tumor suppressor function of PP2A, and NB cells treated with SET or CIP2A siRNA had a decreased malignant phenotype." (PMID 39594793, 2024). "This study demonstrated that PF targets and degrades CIP2A protein, inhibits the PI3K/AKT pathway and c‐Myc activity, and induces tumor cell apoptosis." (PMID 39399646, 2024). "As an endogenous inhibitor of PP2A, CIP2A interacts with the B56α and B56γ subunits of PP2A, forming a CIP2A‐B56α‐PP2Ac pseudo‐trimer, thereby inhibiting PP2A's tumor‐suppressive functions." (PMID 39399646, 2024). "For example, metformin induces CIP2A degradation via the UPS pathway, thereby affecting tumor metabolic plasticity." (PMID 39399646, 2024). "Three of the studies investigated reported on tumor tissue vs non-tumor tissue (GSE15471, GSE16515 and GSE101448), and in all these, we found an upregulation of KIAA1524/CIP2A, TIPRL, STRN and ARPP19, and a reduced expression of PPP2R1B in the tumor." (PMID 37170215, 2023). "For instance, in breast cells, LINC00665 was shown to encode for a micropeptide of 5.5 kDa named CIP2A-BP, which binds CIP2A and competes with the subunit PP2A, an oncogene that promotes tumor progression." (PMID 36901971, 2023). "CIP2A is an important oncogene that inhibits the activity of PP2A, thereby maintaining the malignant phenotype of tumor cells and playing an important role in the occurrence, development, and biological behavior of tumor cells." (PMID 37810976, 2023). "The presence of CIP2A and MYC at the NPC signifies that the tumor suppressive activity of PP2A-B56α is likely inhibited, potentially promoting oncogenic signaling though a PP2A-B55α-MYC axis." (PMID 35118387, 2022). "Depletion of CIP2A expression in GBM cells induces senescence and prevents tumor growth in vitro and in vivo." (PMID 36555359, 2022). "CIP2A inactivates protein phosphatase 2A (PP2A), which reduces the phosphorylation of Akt (protein kinase B) and stabilizes the c-Myc proto-oncogene in tumor cells." (PMID 36313570, 2022). "In particular, this review is focused on the role of CIP2A, an inhibitor of PP2A, which through stimulating cell proliferation and survival, evasion of senescence, and apoptosis inhibition, increases tumor cell growth." (PMID 36555359, 2022). "Cancerous inhibitor of protein phosphatase 2A (CIP2A), which inhibits protein phosphatase 2A (PP2A) activity, promotes malignant cell transformation and tumor growth by inhibiting the tumor suppressor activity of PP2A." (PMID 34513828, 2021). "PP2A is a tumor suppressor that is activated by FTY720, either directly or by inhibition of the inhibitors of PP2A –CIP2A and I2PP2A." (PMID 30969990, 2019).
tumor (continued). "Cancerous inhibitor of protein phosphatase 2A (CIP2A) is an endogenous protein phosphatase 2A (PP2A) inhibitor and Myc stabilizer, which is reported to promote malignant cell transformation and tumor growth." (PMID 30671469, 2018). "Future studies will address the relative tumor initiating capacities of PP2A and its known regulators, inhibitor of PP2A (CIP2A) and SET (I2PP2A) both alone and in concert, using similar reconstitution assays." (PMID 26563471, 2015). "CIP2A and p-PP2A were expressed mainly in the cytoplasm of cancerous cells and diffusely distributed in the tumor." (PMID 25726524, 2015). "CIP2A, an endogenous inhibitor of protein phosphatase 2A (PP2A), is a recently identified oncogene, which is overexpressed in several tumour types at a very high frequency." (PMID 25965834, 2015). "In patient samples of HNSCC, CIP2A was expressed in 82.7% and Oct4 in 36.5% of the studied tumor samples, respectively, and all Oct4 positive HNSCC tumours were also CIP2A positive." (PMID 25474139, 2015). "The result of the study demonstrate that the EGFR-MEK1/2-ETS1 pathway is a critical positive regulator of CIP2A expression revealing a potential link between deregulated EGFR-MEK1/2-ETS1 pathway signaling and CIP2A-dependent tumor growth." (PMID 25015035, 2014). "The inhibition of CIP2A by bortezomib leads to PP2A-dependent Akt inactivation and tumor cell apoptosis." (PMID 24307892, 2013). "CIP2A has been shown to stabilize c-Myc oncoprotein by inhibiting PP2A activity toward c-Myc, thus promoting anchorage-independent cell growth and in vivo tumor formation." (PMID 23383345, 2013). "Our in vivo data also showed bortezomib downregulated CIP2A in HCC-1937 xenograft tumors and inhibited their tumor growth." (PMID 22537901, 2012). "We further analysed CIP2A protein level in 107 RCC tissues, 19 tumour adjacent tissues and 6 normal renal tissues using an immunohistochemical approach." (PMID 22075943, 2011). "Based on the role of CIP2A in stabilising and up-regulating the MYC oncoprotein, it is likely that MYC is involved in CIP2A-stimulated invasiveness of tumour cells." (PMID 22075943, 2011). "Also, cancerous inhibitor of protein phosphatase 2A (CIP2A) enhances oxidative phosphorylation by promoting tetramer PKM2 formation and redirecting PKM2 to mitochondria, thereby promoting tumor progression." (PMID 41211480, 2025). "TD-19 and afatinib induce apoptosis and tumor suppression in EGFR wild-type or mutation-negative NSCLC through CIP2A inhibition, with afatinib also blocking ELK-1-mediated CIP2A transcription." (PMID 40943297, 2025). "Additionally, CIP2A-mediated PP2A inhibition results in increased Akt phosphorylation, contributing to tumor growth and metastasis." (PMID 41155727, 2025). "Mechanistically, UCHL1 interacted with CIP2A as a DUB, thereby promoting tumor progression in GC." (PMID 41155583, 2025). "CIP2A/p90 plays an important role in the proliferation, apoptosis, invasion, migration, epithelial–mesenchymal transition (EMT), cell cycle, and drug resistance of different tumor cells." (PMID 36911405, 2023). "The inhibitory activity of PP2A by overexpression of SET and CIP2A increases hyper-phosphorylated proteins, including pS62-MYC and pAkt, and induces proinflammatory cytokines TNF-α and IL-1, which are presented as essential molecules in tumor promotion." (PMID 37097392, 2023). "In addition, recent studies showed that CIP2A is an endogenous inhibitor of PP2A in malignant cells, thereby promoting the transformation of defective cells into malignancy and tumor growth." (PMID 36555359, 2022). "Therefore, the combination of CIP2A and the NLR can reflect non-tumour factors, such as the inflammation, immune status, and nutritional status of the body, which can provide a more comprehensive assessment of the preoperative condition of CRC patients." (PMID 34144694, 2021).
tumor (continued). "We and others have shown that CIP2A regulates MYC, is essential for tumor growth, tissue regeneration, and thus may open a therapeutic window for targeting tumors." (PMID 33078202, 2021). "Similarly, we also found that silencing the expression of CIP2A suppressed CRC cell proliferation, growth and xenograft tumor growth in vivo." (PMID 32321509, 2020). "In contrast, detection of CIP2A or PME-1 overexpression in (type I) EC cannot rely on genetic methods, but should rather focus on the mRNA or protein level, and is therefore, much more dependent on the availability of tumor biopsies or resected tumor material." (PMID 31214504, 2019). "Tumor tissues isolated from mice also showed that CuB inhibited EGFR and CIP2A expression in vivo." (PMID 30759826, 2019). "In 16 cases MM tissues with paired adjacent non-tumor tissues, we observed a significantly higher expression of CIP2A in tumor tissues compared with paired adjacent non-tumor tissues (P<0.05)." (PMID 29263916, 2017). "Importantly, lapatinib showed anti-tumor activity in mice bearing MDA-MB-468 xenograft tumors, and suppressed CIP2A as well as p-Akt in these xenografted tumors." (PMID 26824320, 2016). "CIP2A expression was not significantly correlated with sex, age, initial stage at diagnosis, location of primary tumor, pathology, grade, margin, distribution of liver metastasis, number of liver metastases, size of liver metastasis or extrahepatic metastasis." (PMID 25896895, 2015). "The radioresistance phenotype of Oct4/CIP2A double positive cells is indicated by various lines of evidence extending from radioresistant normal testicular cell population in vivo, to both HNSCC tumor tissues and cell lines." (PMID 25474139, 2015). "CIP2A promotes malignant cell transformation and tumour growth, and importantly its downregulation does not cause detrimental systemic side effects in vivo." (PMID 25474139, 2015). "To further explore whether CIP2A was required for NPC tumor growth in vivo, we conducted xenograft tumor model assays by subcutaneously injecting SUNE-1 cells stably expressing shCIP2A or scrambled control siRNA into the dorsal flank of several mice." (PMID 24884612, 2014). "CIP2A overexpression positively correlated with advanced FIGO stage and tumor grade." (PMID 25015035, 2014). "The depletion of CIP2A expression inhibited c-Myc protein expression in NPC cell lines, suppressed cell viability, colony formation, and anchorage-independent growth in vitro, and inhibited xenograft tumor growth in vivo." (PMID 24884612, 2014). "The lack of physiological function of CIP2A in an adult organism raises the question regarding its role outside being an inhibitor of the tumor suppressor PP2A." (PMID 25015035, 2014). "Furthermore, silencing CIP2A expression influenced MYC protein expression and further suppressed NPC cell proliferation and tumor growth." (PMID 24884612, 2014). "Furthermore, CIP2A expression level was significantly correlated to the UICC stage, lymph node metastasis, distant metastasis, and histological tumour grading." (PMID 24098375, 2013). "All these effects of MYC may contribute to tumour cell metastasis driven by CIP2A, and further study is required to elucidate the role of MYC in CIP2A-mediated RCC metastasis." (PMID 22075943, 2011). "A recent study in NSCLC further revealed that CIP2A binds to pyruvate kinase M2 (PKM2), inducing tetramer formation, redirecting PKM2 to mitochondria, and enhancing oxidative phosphorylation and B-cell lymphoma 2 (Bcl-2) phosphorylation—thereby boosting tumor cell energy metabolism and survival." (PMID 40943297, 2025). "The feedback loop involving IL-10, CIP2A, and CREB phosphorylation may impact tumor progression." (PMID 38273373, 2024).
tumor (continued). "We hypothesized that identifying parameters reflecting both tumour characteristics and the host SIR may be a good approach for reflecting patient survival and that COCN (combination of CIP2A and NLR) may be a good biomarker for the prognostic assessment of CRC." (PMID 34144694, 2021). "While its role in tumor progression is still underexplored, a recent study revealed that ARPP19 mRNA expression is an independent predictor for relapse in AML, and it might promote cell survival by regulating CIP2A and MYC expression." (PMID 32110991, 2020). "In this study, we identified an auto-regulatory feedback loop Cip2a/miR-301a represent a new unifying mechanism of TNBC progression, which might promise to allow multiple therapeutic interventions aimed at blocking its pro-tumor activity." (PMID 31762806, 2019). "Therefore, CIP2A inhibition could be a viable strategy to post-translationally target PP2A and inhibit tumor growth in MM." (PMID 29263916, 2017). "Moreover, IHC staining of the tumor tissues illustrated that percentage of PCNA positively stained cells in FN (+) sh-Control group was significantly higher than both FN (-) sh-Control group and FN (+) sh-CIP2A group." (PMID 28521777, 2017). "As we detailed in material section, this compound was originally developed to enhance PP2A via targeting another PP2A inhibitor, CIP2A, but whether the additive CIP2A suppression contributed to better anti-tumor effects of EMQA was not clear." (PMID 26575017, 2016). "Cancerous inhibitor of protein phosphatase 2A (PP2A; CIP2A) was first identified as a novel endogenous interacting partner of PP2A, which is a serine/threonine phophatase and may function as a tumor suppressor." (PMID 25650660, 2015). "In addition, we explored the potential role of CIP2A in NPC cell proliferation and tumor growth, which could help to better understand the pathology of NPC and may further provide a novel therapeutic target for the treatment of NPC patients." (PMID 24884612, 2014). "Even though the interaction between miR-383 and CIP2A has not been previously reported in OvCa, we could suggest that miR-383 could exert its tumour suppressive properties via targeting the genes, consequently leading to tumour growth inhibition." (PMID 40594400, 2025). "While there is a general lack of studies on the predictive potential of CIP2A expression in EC models, it is very likely that, based upon the evidence obtained in other solid (gynecologic) tumors, CIP2A expression could mediate therapeutic resistance in EC cells as well." (PMID 31214504, 2019). "Staining intensity of CIP2A was categorized to three different groups (negative, low or high) whereas Oct4 exhibited either negative or positive staining in HNSCC tumours." (PMID 25474139, 2015). "Given CIP2A’s activation of oncogenic and metabolic pathways (e.g., c-Myc, AKT, PKM2), E-cadherin expression in this setting may represent phenotypic adaptation rather than tumor suppression." (PMID 40943297, 2025). "Although our in vivo data show that tamoxifen inhibited tumor growth and downregulated protein levels of CIP2A in MDA-MB-468 xenograft tumors, we did not observe markers of apoptosis or proliferation and our results do not validate the role of CIP2A in tamoxifen-induced apoptosis in vivo." (PMID 25228280, 2014).
hematological malignancies (4 papers, 2014 to 2023). "Likewise, CIP2A have been found overexpressed in hematological malignancies and in solid tumors, and to be associated with high proliferation rate and poor prognosis." (PMID 25763353, 2015).
infection (4 papers, 2015 to 2022). The state of being infected such as from the introduction of a foreign agent such as serum, vaccine, antigenic substance or organism. "To explore the mechanism by which E6 regulates CIP2A, we utilized retrovirus‐mediated successive infection to establish PHKs expressing wild‐type HPV‐16E6." (PMID 29893470, 2018). "To explore whether CIP2A is directly modulated by HPV-16E7, we established PHKs expressing HPV-16E7 by retrovirus-mediated successive infection; the expression was confirmed by RT-PCR." (PMID 25650660, 2015).
immune diseases (1 paper, 2016). "Also, our results demonstrate that CIP2A is downstream of Zap70 activity during T-cell activation, which is interesting considering the role for Zap70 in human immune diseases." (PMID 27100879, 2016).
neurological diseases (1 paper, 2022). "Interestingly, CIP2A is mainly expressed in the central nervous system, suggesting that CIP2A might strongly correlate with neurological diseases." (PMID 34984583, 2022).
CIP2A also shares sentences with these, for which no sentence is quoted: B-cell lymphoma (2 papers); clear cell renal cell carcinoma (2); Prostate Tumors (2); acute lymphoblastic leukemia (1); adenocarcinoma (1); bacterial infection (1); bacterial vaginosis (1); benign tumor (1); bladder urothelial carcinoma (1); Burkitt lymphoma (1); cervical intraepithelial neoplasia (1); cervical squamous cell carcinoma (1); epithelial dysplasia (1); Esophagogastric Junction Adenocarcinoma (1); fibrosarcoma (1); fibrosis (1); gastric adenocarcinoma (1); H. pylori (1); hematological cancers (1); high blood pressure (1); Hyperglycemia (1); Hypoalbuminemia (1); inflammatory pseudotumor (1); intestinal obstruction (1); laryngeal carcinoma (1); leukoplakia (1); Listeria monocytogenes Infection (1); liver abscesses (1); lung squamous cell carcinoma (1); lymphoma (1).
A further 17 diseases each share a sentence with CIP2A in 1 paper.